TRIM29 (tripartite motif containing 29)
Description:
Plays a crucial role in the regulation of macrophage activation in response to viral or bacterial infections within the respiratory tract. Mechanistically, TRIM29 interacts with IKBKG/NEMO in the lysosome where it induces its 'Lys-48' ubiquitination and subsequent degradation. In turn, the expression of type I interferons and the production of pro-inflammatory cytokines are inhibited. Additionally, induces the 'Lys-48' ubiquitination of STING1 in a similar way, leading to its degradation.
Synonyms: ATDC; FLJ36085
Tractability: PROTAC: ubiquitination databases record sites on it.
Gene: Protein-coding gene on chromosome 11 (120,111,286 to 120,185,529, reverse strand). Ensembl gene ENSG00000137699.
Subcellular location: Cytoplasm; Lysosome
Subcellular location (Human Protein Atlas): Intermediate filaments; Cytosol; Nucleoplasm
Pathways (Reactome):
Immune System: Interferon gamma signaling
Gene Ontology:
Molecular function: cadherin binding involved in cell-cell adhesion; identical protein binding; protein binding; zinc ion binding
Biological process: cell-cell adhesion
Cellular component: adherens junction; cytosol; lysosome; cytoplasm
Genetic constraint (gnomAD): Loss-of-function variants: 52 observed, 56.77 expected, observed/expected ratio (o/e) 0.92, 90% interval 0.73 to 1.15. The upper end of that interval is the gene's LOEUF score, 1.15, which puts it in group 5 of 6, group 1 being the genes least tolerant of losing a copy. Missense variants: 753 observed, 789.48 expected, observed/expected ratio (o/e) 0.95, 90% interval 0.9 to 1.01. Synonymous variants: 319 observed, 321.17 expected, observed/expected ratio (o/e) 0.99, 90% interval 0.91 to 1.09.
Homologues: Orthologues: chimpanzee TRIM29 (99% identical), macaque TRIM29 (99% identical), guinea pig TRIM29 (91% identical), pig TRIM29 (91% identical), rat Trim29 (91% identical), mouse Trim29 (89% identical), dog TRIM29 (85% identical), rabbit TRIM29 (77% identical), tropical clawed frog trim29 (36% identical). Paralogues in human: TRIM39 (15% identical), TRIM25 (14% identical), TRIM41 (14% identical), TRIM32 (14% identical), TRIM11 (13% identical), TRIM68 (13% identical), TRIM16 (13% identical), MID2 (13% identical), TRIM47 (13% identical), TRIM27 (13% identical), TRIM6 (13% identical), MEFV (13% identical), and 68 more.
Diseases named in the same sentence as TRIM29 in open-access papers:
TRIM29 is named in the same sentence as 106 diseases in open-access papers, as found by Europe PMC text mining. Sharing a sentence is not in itself a finding about the gene and the disease. The quoted sentences say what the papers report.
gastric cancer (21 papers, 2010 to 2026). A primary or metastatic malignant neoplasm involving the stomach. "Reduced expression of TRIM29 in gastric cancer samples was associated with advanced tumor stages, lower CD8+ immune cell infiltration, and poorer survival outcomes in clinical sample analysis." (PMID 39768197, 2024). "Determining TRIM29 expression in preoperative gastroscopic biopsy tissue is of great value for predicting lymph node metastasis of gastric cancer before surgery." (PMID 40936722, 2025). "TRIM29 also demonstrated prognostic significance in postoperatively resected gastric cancer patients, with its expression identified as an independent prognostic indicator for overall survival." (PMID 40936722, 2025). "Knockdown of TRIM29 in gastric cancer cells SGC-7901 and MGC80-3 led to decreased β-catenin levels, as shown in vitro through siRNA-mediated experiments." (PMID 39768197, 2024). "The elevated expression of TRIM29 in colorectal cancer, gastric cancer, and lung cancer leads to an increase in the invasive phenotype of malignant tumors, while in breast cancer and Merkel cell carcinoma plays an inhibitory role." (PMID 38213743, 2024). "It highlights the necessity for further studies to reveal the specific role of TRIM29 in gastric cancer development." (PMID 39768197, 2024). "Overexpression of TRIM29 in gastric cancer has been reported to play an oncogenic role in cancer development and metastasis." (PMID 35845310, 2022). "Several studies have shown that TRIM29 expression is significantly upregulated in a variety of tumours, such as colorectal cancer, gastric cancer, and lung cancer, and that the high expression of TRIM29 is closely related to its prognosis." (PMID 34353343, 2021). "Previous studies confirmed that TRIM29 is regulated by varying miRNAs, such as miR-185 in gastric cancer and miR-621 in bladder cancer." (PMID 33495406, 2021). "Recent studies verified TRIM29 as an oncogene in many kinds of cancers, such as bladder, pancreatic, and gastric cancer." (PMID 33495406, 2021). "In cancer study, TRIM29 had been suggested that it was up-regulated expression in multiple cancer types such as pancreatic cancer, gastric cancer, colorectal cancer, lung cancer, bladder cancer, ovarian cancer, endometrial cancer, and multiple myeloma." (PMID 32640423, 2020). "For example, in gastric cancer overexpression of TRIM28 and TRIM29 is associated with increased cell proliferation and a poor prognosis in patients." (PMID 30089913, 2019). "Another study found that TRIM29 functions as an oncogene in gastric cancer, the miR-185-TRIM29 axis regulates gastric cancer cell growth and apoptosis through Wnt/β-catenin pathway inactivation in vitro." (PMID 27145374, 2016). "However, recent in vivo and in vitro investigations demonstrate that TRIM29 enhances anti-tumor T cell immunity via the IGF2BP1/PD-L1 axis in gastric cancer." (PMID 40936722, 2025). "Early studies identified TRIM29 as a molecular marker for lymph node metastasis in gastric cancer." (PMID 40936722, 2025). "TRIM29 expression pertains to the poor prognosis of gastric cancer and cervical cancer." (PMID 37628777, 2023). "TRIM25 and TRIM29 overexpression can both enhance the malignant degree of gastric cancer." (PMID 37628777, 2023). "TRIM29 expression is associated with poor prognosis in various cancers, including cervical, pancreatic, lung, esophageal, and gastric cancers, but not in other cancers, such as squamous cell carcinoma." (PMID 35054873, 2022). "TRIM29 is important in differentiation, proliferation, and development of gastric cancer, but this gene might be responsible for differentiation and proliferation in pituitary prolactinoma." (PMID 33709028, 2021).
gastric cancer (continued). "TRIM29 promotes immune cell infiltration in the gastric cancer (GC) microenvironment, enhancing anti-tumor immunity." (PMID 39223632, 2024). "Notably, another research team found that TRIM29 was upregulated in human gastric cancer tissues." (PMID 39768197, 2024). "Although few studies have reported an elevated TRIM29 expression in gastric cancer (GC), its clinicopathological and prognostic values as well as possible molecular mechanisms are yet to be re-evaluated in different populations." (PMID 35845310, 2022). "Our results showed that TRIM29 is overexpressed in GC and is correlated with shorter overall survival and poor clinical outcomes, confirming the oncogenic role of TRIM29 in gastric cancer." (PMID 35845310, 2022). "Indeed, while the abundance of TRIM29 is reduced in melanoma, in breast and in prostate cancer, its abundance is induced and correlated with the severity of gastric cancer suggesting that function and role of TRIM29 in carcinogenesis may depend on the organ." (PMID 20454669, 2010). "In cancer biology, linc00324 suppresses TRIM29 via miR-195-5p upregulation, inhibiting thyroid papillary carcinoma proliferation and invasion, while ELFN1-AS1 promotes gastric cancer progression by suppressing miR-211-3p and upregulating TRIM29." (PMID 39973927, 2025). "Knockdown of TRIM29 in the gastric cancer cell line MGC803 decreased the expression levels of β-catenin, cyclin D1, and c-Myc, indicating that TRIM29 plays a role as an oncogene in gastric cancer." (PMID 38213743, 2024). "TRIM29 negatively regulates migration and invasion of squamous cell carcinomas (SCC) and exerts an opposite oncogenic role in CRC, non-small cell lung carcinoma (NSCLC), lung squamous cancer and gastric cancer (GC)." (PMID 31137886, 2019).
bladder cancer (18 papers, 2016 to 2026). "We have also shown that TRIM29 is enriched in basal bladder cancer subtypes and is part of a TP63-regulated program that promotes migration and invasive progression." (PMID 42239777, 2026). "Direct impact of TRIM29 is noticeable in bladder cancer, where Bcl family protein and cyclin D1/E levels are enhanced by TRIM29 through the PKC-NF-κB signaling pathway thus resulting in reduced apoptosis with an increase in proliferation signal." (PMID 40420099, 2025). "Fourteen TRIM family proteins were associated with bladder cancer (tumor-promoting: TRIM9, TRIM25, TRIM26, TRIM28, TRIM29, TRIM59, TRIM65, and TRIM66; tumor-suppressive: TRIM19 and TRIM38)." (PMID 40723250, 2025). "Here we identify stimulation of bladder cancer migration as the specific role of TRIM29 during invasion." (PMID 38168254, 2023). "Overexpression of tripartite motif 29 (TRIM29) upregulated the levels of cell survival-related proteins (e.g., cyclin and Bcl family) and inhibited cisplatin-mediated cell apoptosis in bladder cancer cells." (PMID 36358843, 2022). "TRIM29 appears to be a highly sensitive marker for cells showing squamous differentiation in urinary bladder carcinoma." (PMID 35204409, 2022). "In bladder cancer, the overexpression of TRIM29 suppresses miR-29 and subsequently activates DNA methyltransferase 3A (DNMT3A), resulting in DNA methylation and silencing of tumor suppressor PTEN." (PMID 34988104, 2021). "TRIM29 is also recognized as an oncogene, and elevated gene expression in multiple tumors such as colorectal cancer and bladder cancer and so on." (PMID 33842346, 2021). "Similar research indicated that TRIM29 overexpression facilitated the proliferation of bladder cancer cells by the activation of NF-κB." (PMID 34917077, 2021). "TRIM29 can enhance expression of DNMT3A by suppressing miR-29 in bladder cancer cells, leading to DNA methylation and silencing of the tumor suppressor PTEN." (PMID 27081037, 2016). "Furthermore, in the TCGA bladder cancer data set, an increase correlation of TRIM29 was found with the basal genes P63, KRT5 and KRT6A suggesting a prominent role of these molecules in aggressive bladder cancers." (PMID 36293167, 2022). "Moreover, TRIM29 is specifically expressed in prostate basal cells, uterine cervical cancer cells and basal subtype bladder cancer cells." (PMID 35204409, 2022). "A recent study demonstrated that TRIM29 was enriched in basal bladder cancers." (PMID 32822399, 2020). "Clinically, upregulated TRIM29 leads to tumor progression or poor prognosis in gastric cancer, prostate cancer, pancreatic adenocarcinoma, lung cancer, nasopharyngeal carcinoma, as well as bladder cancer." (PMID 27081037, 2016). "Further, urothelial Trim29 KO enriches immune cell recruitment to the bladder and upregulates STING and inflammatory signaling in mouse and human bladder cancers." (PMID 42239777, 2026). "Moreover, by activating DNA methyltransferase 3 A, TRIM29 indirectly suppresses PTEN via epigenetic regulation and contributes to poor prognosis in bladder cancer." (PMID 40420099, 2025). "We have previously shown that TRIM29, also known as ATDC, is transcriptionally regulated by TP63 in basal bladder cancers where it promotes invasive progression and metastasis, but the molecular events which promote invasion and metastasis downstream of TRIM29 remained poorly understood." (PMID 38168254, 2023). "More specific, TRIM29 protein has been shown to be a driver of invasive and non-invasive bladder cancer." (PMID 36352089, 2022). "TRIM29 (also known as ATDC), a member of the tripartite motif protein family, has been shown to play oncogenic roles in various cancers, including pancreatic cancer, thyroid cancer, bladder cancer, and CRC." (PMID 34922544, 2021).
bladder cancer (continued). "The same study found TRIM29 gene expression to be correlated to KRT5, KRT14, KRT6A, and KRT16 expression using The Cancer Genome Atlas (TCGA) RNA sequencing data from multiple tumor types, including basal subtype bladder cancers." (PMID 32822399, 2020). "Interestingly, TRIM29-driven bladder cancers in transgenic mice were indistinguishable from gene expression signatures of human bladder cancers." (PMID 36352089, 2022).
colorectal cancer (18 papers, 2011 to 2025). A primary or metastatic malignant neoplasm that affects the colon or rectum. "For example, TRIM29 is upregulated in colorectal cancer, and other tumours whereas it is downregulated in breast cancer, and other tumours." (PMID 37671092, 2023). "The increased expression of Tripartite Motif 29 (TRIM29) was positively correlated with lymph node metastasis and β-catenin expression in patients with colorectal cancer." (PMID 35836256, 2022). "Mechanism studies have shown that TRIM29 can activate the Wnt/β-catenin signaling pathway by up-regulating the expression of CD44 in colorectal cancer." (PMID 35836256, 2022). "In colorectal cancer, TRIM29‐overexpressed cells also showed VIM activation contributing to migration, invasion and metastases." (PMID 36420658, 2022). "More interestingly, TRIM29 is much more highly expressed in right-sided colorectal cancer (RSCC) than in left-sided colorectal cancer (LSCC)." (PMID 33495406, 2021). "TRIM29 degrades PKM1 and causes the glucose metabolism of colorectal cancer cells flowing from oxidative phosphorylation to glycolysis." (PMID 33495406, 2021). "TRIM29 can inhibit or activate the progression of hepatocellular carcinoma and colorectal cancer by targeting Wnt/β‐catenin signaling pathway." (PMID 33118318, 2020). "Notably, TRIM29 is overexpressed in lung cancer, osteosarcoma, pancreatic cancer, gastric cancer and colorectal cancer." (PMID 40420099, 2025). "TRIM29 expression was higher in patients with higher TIL and proved to be related to immune dysfunction in colorectal cancer." (PMID 37251404, 2023). "The miR- 761/TRIM29/PHLPP1 axis is activated by circL4R to facilitate the proliferation and spread of colorectal cancer cells." (PMID 36673815, 2023). "TRIM2, TRIM28, TRIM29, TRIM59, and other TRIM family are relevant to malignancy of neurologic tumors such as glioma and digestive tumors such as gastric cancer, colorectal cancer." (PMID 33118318, 2020). "TRIM29 overexpression leads to an increased CD44 expression, which activates the Wnt-β-catenin signaling pathway and results in enhanced migration and invasion in colorectal cancer." (PMID 40420099, 2025). "Besides, TRIM29 promoted EMT-mediated invasion and metastasis of colorectal cancer by activating Wnt/β-catenin signaling pathway." (PMID 34917077, 2021).
ovarian carcinoma (17 papers, 2021 to 2025). A malignant neoplasm originating from the surface ovarian epithelium. "In ovarian cancer, TRIM29 expression is associated with poor prognosis and is increased in the cisplatin-resistant ovarian cancer cells with increased cancer stem cell-like properties." (PMID 35054873, 2022). "Furthermore, overexpression of tripartite motif-containing 29 (TRIM29) is closely associated with adverse clinical outcomes in ovarian cancer and promotes the proliferation, migration, and invasion of ovarian cancer cells via the SETBP1/SET/PP2A carcinogenic signal axis." (PMID 35898891, 2022). "Recent research has indicated that recruitment of YTHDF1 to m6A-modified TRIM29 is involved in promoting TRIM29 translation in cisplatin-resistant ovarian cancer cells." (PMID 39695760, 2024). "TRIM29 is also an important innate immunomodulator, which upregulates TRIM29 translation in cisplatin-resistant ovarian cancer cells through YTHDF1-mediated m6A modification." (PMID 39403369, 2024). "SETBP1 has been identified as a key target of TRIM29, and the SETBP1/SET/PP2A axis has been shown to be essential for the progression of ovarian cancer driven by TRIM29." (PMID 39273321, 2024). "Mechanisms research indicated that YTHDF1 promotes the CSC-like characteristics of the cisplatin-resistant ovarian cancer cells via recognition of m6A-edited TRIM29 and increased TRIM29 translation." (PMID 36650570, 2023). "TRIM29 is highly expressed in cisplatin-resistant ovarian cancer cells and correlates with poor prognosis in these patients." (PMID 36650570, 2023). "Because the C-terminal region of TRIM29 (amino acids 267–588) is retained in the SPON1-TRIM29 fusion protein, it is possible that the molecule drives stress resistance in ovarian cancer cells in a dominant-positive manner." (PMID 35054873, 2022). "Moreover, TRIM29 has also been shown to contribute to chemoresistance in lung cancer and ovarian cancer." (PMID 40420099, 2025). "In ovarian cancer, YTHDF1 enhances the resistance of ovarian cancer cells to cisplatin, which may result from the maintenance of ovarian cancer CSCs through interaction with TRIM29." (PMID 37264402, 2023). "In line with the putative tumor-promotive function of SPON1-TRIM29 fusion protein, it may be relevant to dissect each function of SPON1 or TRIM29 in ovarian cancer." (PMID 35054873, 2022). "In addition, YTHDF1 was recruited to the m6A modification site of TRIM29, promoting TRIM29 translation in cisplatin-resistant ovarian cancer cells." (PMID 36017491, 2022). "Recruitment of YTHDF1 to m6A-modified TRIM29 was involved in promoting TRIM29 translation and enhancing the CSC characteristics in cisplatin-resistant ovarian cancer cells." (PMID 34805173, 2021). "In addition, TRIM29 can facilitate SETBP1 transcriptional activation via the vascular endothelial zinc finger 1 (VEZF1) transcription factor, promoting ovarian cancer progression." (PMID 35898891, 2022). "TRIM29 expression levels correlate with prognosis in OC and enhance CSC-like features in cisplatin-resistant OC cells; YTHDF1 promotes TRIM29 translation in an m6A-dependent manner which contributes to the stem cell-like phenotype in cisplatin-resistant ovarian cancer." (PMID 37194218, 2023).